SPEM3 (SPEM family member 3)
Gene: Protein-coding gene on chromosome 17 (7,428,857 to 7,432,820, forward strand). Ensembl gene ENSG00000283439.
Subcellular location: Membrane
Gene Ontology:
Biological process: flagellated sperm motility; sperm individualization
Cellular component: cytoplasm; membrane
Homologues: Orthologues: chimpanzee SPEM3 (98% identical), rat Spem3 (49% identical), mouse Spem3 (49% identical).